FOXO3 (forkhead box O3)
Diseases named in the same sentence as FOXO3 in open-access papers (continued):
Sharing a sentence is not in itself a finding about the gene and the disease.
liver cancer (28 papers, 2013 to 2025). An epithelial or non-epithelial malignant neoplasm that arises from the liver. "Regarding liver cancer, several studies sustain that abnormal FOXO3 overexpression could represent an unfavorable hallmark in HCC, being linked to multidrug resistance, more aggressive phenotypes and a worse long-term prognosis." (PMID 34771514, 2021). "A comprehensive in vitro and in vivo study demonstrated that ATIC facilitates the development of liver cancer via the AKT/FOXO3 pathway." (PMID 39001904, 2024). "For example, m6A methylation regulates sorafenib resistance in liver cancer through FOXO3-mediated autophagy, and m6A-modified circRNA-SORE sustains sorafenib resistance in HCC by regulating β-catenin signaling." (PMID 35494016, 2022). "RNA m6A methylation regulates sorafenib resistance in liver cancer through FOXO3-mediated autophagy in hypoxic TME." (PMID 36457492, 2022). "By regulating FOXO3-mediated autophagy, m6A methylation regulates the drug resistance to sorafenib in liver cancer." (PMID 36561529, 2022). "We found that ATIC inhibited autophagy and promoted liver cancer progression by modulating the AKT/Forkhead box subgroup O3 (FOXO3) pathway." (PMID 34803509, 2021). "ATIC was confirmed to inhibit autophagy and promote the proliferation, invasion and metastasis of liver cancer cells through the AKT/Forkhead box subgroup O3 (FOXO3) signaling pathway in vitro and in vivo." (PMID 34803509, 2021). "Analysis of clinical samples further showed that the levels of METTL3 and FOXO3 expression are closely related in patients with liver cancer are closely related." (PMID 34246319, 2021). "FOXO3 is an important target of m6A modification in the development of therapeutic resistance to sorafenib therapy in liver cancer." (PMID 34246319, 2021). "In a mouse xenograft model, METTL3 deletion significantly enhanced the resistance of liver cancer to sorafenib by disrupting the METTL3-mediated stability of FOXO3 mRNA, while FOXO3 overexpression restored the sensitivity of liver tumours to sorafenib." (PMID 34246319, 2021). "ATIC inhibits autophagy and promotes the progression of liver cancer through the AKT/FOXO3 signaling pathway." (PMID 34803509, 2021). "In this study, we proved through in vivo and in vitro experiments that ATIC promotes the progression of liver cancer through the AKT/FOXO3 pathway." (PMID 34803509, 2021). "Inhibition of FOXO3 phosphorylation could lead to the transport of FOXO3 protein to the cell nucleus, activation of FOXO3 transcriptional activity, and eventually inhibition of the proliferation of liver cancer cells." (PMID 40428322, 2025). "The importance of FOXO3 in oral squamous cell carcinoma as well as in liver cancer was noted." (PMID 38202222, 2023). "In addition, 6,8-diprenylorobol suppressed cell viability and induced apoptosis in human liver cancer cells (HCC) via regulation of FOXO3 and CYP2J2." (PMID 35052675, 2022). "Furthermore, we have suggested that ATIC inhibits autophagy and promotes liver cancer progression through the AKT/FOXO3 pathway." (PMID 34803509, 2021). "Moreover, we found that Met elevated the expression of FOXO3 and FOXO3 are crucial for the progression of liver cancer." (PMID 34546972, 2021). "A wide variety of growth factors are highly expressed in liver cancer, A mixture of several transcriptional stimulators and repressors may control FOXO3 transcriptional regulation." (PMID 31488102, 2019). "Our findings suggest that a CKI-ε-FoxO3/Smad-Bim engine could be considered as a potential target to treat liver cancer." (PMID 25503443, 2015). "However, the roles of FoxO3 in TGF-β-induced apoptosis in liver cancer cells have yet to be fully elucidated." (PMID 25503443, 2015). "Several miRNAs are reported to regulate the expression of FOXO3 in various cell types via directly binding to 3’-UTR, such as miR-155 in liver cancer cells, miR-10b-3p in esophageal squamous cell carcinoma cells, and miR-34a in macrophages." (PMID 33520966, 2020).
liver cancer (continued). "In liver cancer, METTL3 can stabilize FOXO3 mRNA, reducing autophagy and sorafenib resistance." (PMID 37675218, 2023). "METTL3 affects FOXO3 RNA stability in a YTHDF1-dependent manner to inhibit the expression of FOXO3 to inhibit autophagy; The reduced expression of METTL3 increases the number of autophagosomes to activate autophagy in liver cancer cells." (PMID 35141221, 2022). "FOXO3, which is mainly expressed by liver cells, seems to be connected to the development of hepatic disease, but the exact linkage between FOXO3 expression and primary liver cancer has not been uncovered yet." (PMID 34771514, 2021). "Taken together, our findings suggest that there might be a CKI-FoxO/Smad-Bim engine in which Thr32 of FoxO3 is pivotal for TGF-β-induced apoptosis, making it a potential therapeutic target for liver cancer treatment." (PMID 25503443, 2015).
Insulin resistance (26 papers, 2009 to 2026). Increased resistance towards insulin, that is, diminished effectiveness of insulin in reducing blood glucose levels. "Wang Lei 21 studied that up-regulation of miR-29a in rat liver tissue caused down-regulation of FOXO3, which led to insulin resistance." (PMID 33967607, 2021). "For example, in the liver, Sestrin3 has been shown to protect against metabolic stress and insulin resistance, while also modulating FOXO3-mediated ROS regulation." (PMID 39857395, 2025). "First, aging and insulin resistance lead to abnormal activation or suppression of key regulators, including FoxO3, MyoD, and muscle atrophy-specific ubiquitin ligases (e.g., Atrogin-1/MAFbx and MuRF1)." (PMID 40191209, 2025). "In the case of IRS1 (cg21511036), AKT1S1 (cg03813033), ADCY2 (cg12566890 and EHMT2 (cg00210002) are hypomethylated, whereas AKT1 (cg01749142), FOXO3 (15283498), are hypermethylated in subjects with insulin resistance and hypertriglyceridemia." (PMID 30926763, 2019). "The ER stress sensor PERK has been shown to phosphorylate the Forkhead transcription factor 3 (FOXO3) and suppressed FOXO3 exacerbates alcoholic hepatitis and insulin resistance impairing cyclin D function promoting HCC." (PMID 24868470, 2014). "Our data supported that rs2802288*A and rs2802292*G in FOXO3 could improve the status of insulin resistance in longevity subjects." (PMID 25913413, 2015). "In this study, we found that LNK was closely related to insulin resistance and apoptosis of granulosa cells via the AKT/FOXO3 pathway." (PMID 33495419, 2021). "The effect of the miR-122-5p inhibitor on NAFLD did not depend on insulin resistance-mediated PI3K/AKT/mammalian target of rapamycin (mTOR) signaling pathway but rather on the upregulation of its downstream FOXO3." (PMID 35222075, 2022). "Although we failed to observe cardiac dysfunction over 12 weeks of HFD, insulin resistance did develop, as demonstrated by increases in FOXO3 and PTEN levels." (PMID 29016649, 2017). "We first showed that candesartan and azilsartan could alleviate insulin resistance in PA-treated HepG2 cells by fully restoring the impaired insulin-stimulated phosphorylation of AKT and its downstream substrates GSK3β, AS160, FOXO1, and FOXO3." (PMID 37121975, 2023).
ischemic stroke (25 papers, 2015 to 2026). A stroke disorder caused by obstruction of blood flow to the brain, due to thrombotic (local blood clot formation) or embolic (due to a blood clot or other material traveling from another site) event. "FOXO3 has been reported to be associated with ischemic stroke and may participate in regulation of autophagy." (PMID 30945454, 2019). "In our study, we demonstrated that intracerebral implantation of FOXO3-engineered human mesenchymal stem cells (F3-MSCs) advances functional recovery in mice after ischemic stroke induced by middle-cerebral-artery-occlusion (MCAO)." (PMID 39820392, 2025). "Our research suggests that FOXO3-engineered MSCs and their corresponding exosomes have a promising potential to be developed into therapeutic strategies for treating ischemic stroke." (PMID 39820392, 2025). "KCNQ1OT1 also mediates ischemic stroke-induced cellular damage by acting as a sponge for miR-153-3p, which leads to the upregulation of Forkhead box O3a (Foxo3)." (PMID 39021183, 2024). "A FOXO3‐related pathway is involved in ketone neuroprotection against ischemic stroke (Yin, Han, Tang, Liu, & Shi, 2015)." (PMID 30945454, 2019). "Additionally, Foxo3 induced autophagy in ischemic stroke damage by directly promoting the expression of ATG7 as a transcription factor." (PMID 39021183, 2024). "Thus, the UPRmt protects neural viability and mitochondrial homeostasis, and the Sirt3/Foxo3/Sphk1 pathway is a promosing therapeutic candidate for ischemic stroke." (PMID 37705748, 2023). "Suppression of the inflammation by targeting miR-19a/b-3p/SIRT1/FoxO3/SPHK1 could be a promising avenue to improve the outcome of ischemic stroke." (PMID 34051800, 2021). "We thus hypothesized that miR-19a/b-3p function through targeting SIRT1/FoxO3 axis in ischemic stroke." (PMID 34051800, 2021). "For example, FOXO3 enhances cell autophagy so as to promote ischemic stroke." (PMID 33791290, 2020). "Additionally, overexpressed FOXO3 plays a deteriorative role in ischemic stroke by stimulating neuronal cell death." (PMID 33791290, 2020). "Based on our results, GSH may prevent the degradation of the tight junction protein claudin-5 following ischemic stroke, which may involve the reduced translocation of FOXO3 into the nucleus." (PMID 25722793, 2015). "In models of ischemic stroke, its upregulation exacerbates neuronal injury via the AKT/FOXO3 pathway." (PMID 41602154, 2026). "In models of ischemic stroke, upregulation of FKBP51 enhances autophagy and inflammatory responses through pathways such as AKT/FoxO3, thereby amplifying brain injury." (PMID 41602154, 2026). "On the other hand, the predominant expression of FOXO3 in neuronal N2a cells could be underlying, among other factors, canonical autophagy activation as previously shown in the neuronal HT22 cell line under oxidative stress, ischemic stroke, and in a mouse model of Huntington disease." (PMID 39768160, 2024). "AGK2 also downregulates the forkhead box O3 (FOXO3a) and mitogen-activated protein kinase (MAPK) signaling pathways, which confer neuroprotection in ischemic stroke." (PMID 35813508, 2022). "We have demonstrated that SIRT3 protects the brain from ischemic stroke by modulating superoxide dismutase 2 (SOD2) and the forkhead box O3a (FoxO3a)." (PMID 31208274, 2019).
non-small cell lung carcinoma (25 papers, 2015 to 2026). A group of at least three distinct histological types of lung cancer, including non-small cell squamous cell carcinoma, adenocarcinoma, and large cell carcinoma. "For example, FOXO3-induced transcription of ATG7 promote autophagy in non-small-cell lung cancer." (PMID 35338124, 2022). "Moreover, CASC11 targets the miR-498/FOXO3 axis and accelerates the proliferation and cell cycle progression of non-small-cell lung cancer." (PMID 33937069, 2021). "Furthermore, the downregulation of Foxo3 promotes cell proliferation, migration, and invasion in non-small cell lung cancer cells by targeting miR-155." (PMID 34555810, 2021). "In cisplatin-resistant non-small cell lung cancer (NSCLC) cells, elevated lactate levels suppress the expression of Forkhead box O3 (FOXO3) through YTH N6-methyladenosine RNA binding protein 2 (YTHDF2)-mediated N6-methyladenosine (m6A) modification." (PMID 41152975, 2025). "Additionally, disruption of circFOXO3 decreased FOXO3 expression, which promoted EMT in non-small-cell lung carcinoma (NSCLC)." (PMID 31027496, 2019). "Accordingly, crizotinib, an FDA-approved drug used for the treatment of patients with ALK-positive and ROS1-positive non-small cell lung carcinoma (NSCLC), triggered the nuclear translocation of FOXO3 suggesting an important role of RTKs such as ALK, MET or ROS1 in the regulation of FOXO3." (PMID 36080182, 2022).
Alzheimer disease (24 papers, 2012 to 2026). A progressive, neurodegenerative disease characterized by loss of function and death of nerve cells in several areas of the brain leading to loss of cognitive function such as memory and language. "Loss of FOXO3 was associated with altered metabolism and function of astrocytes, increased β-amyloid plaques, a pathological hallmark of Alzheimer’s disease, and synapse loss." (PMID 37891184, 2023). "When compared to reference populations in Italy and Greece, LBZ populations show lower frequencies in genetic risk markers in APOE4, APOE2, and the TT allele of FOXO3, which are associated with an increased risk for Alzheimer’s disease and decreased cognitive function." (PMID 39039045, 2024). "However, there is also evidence that Foxo3 activation is associated with neuronal death, while phosphorylation of Foxo3 and its movement away from the nucleus would attenuate Alzheimer's disease (AD) – type amyloid neuropathology and preserve spatial reference memory." (PMID 40859434, 2025). "Combined with the reduced expression of FoxO3 in the aging brain, our results support the concept that elevating astrocytic FoxO3 may reverse cortical astrogliosis and associated functional impairment in aging and Alzheimer's disease." (PMID 34247441, 2021). "Overall, FOXO3 expression in astrocytes seems to protect the brain from aging and from Alzheimer’s disease." (PMID 37891184, 2023). "Cyclin-dependent kinase-5 (Cdk5) increases amyloid beta levels through FOXO3 activity and induces the pathogenesis of Alzheimer’s disease." (PMID 31323047, 2019). "Interestingly, AKT1, MAPK8, BCL2L1, FOXO3, and CTNNB1 were not only significantly associated with pathogenic genes (APP, MAPT, and PSEN2) but also with longevity in Alzheimer’s Disease." (PMID 36620771, 2022). "Interestingly, a recent study showed that FOXO3 is a direct target of miR-212 in the neurons of patients with Alzheimer's disease." (PMID 24519909, 2014).
chronic myeloid leukemia (22 papers, 2010 to 2024). "This is in agreement with research which has shown that nuclear localization of FOXO3 is required for CSC survival in chronic myeloid leukaemia (CML)." (PMID 29180117, 2018). "In the cancer stem cells of chronic myeloid leukemia, FOXO3 is enriched in the nucleus and essential for maintaining these cancer stem cells." (PMID 22916022, 2012). "Activation of FoxO3 antagonizes cell proliferation and promotes apoptotic cell death in chronic myelogenous leukemia cell lines." (PMID 22489133, 2012). "In chronic myelogenous leukemia, a tyrosine kinase inhibitor (imatinib) activated FOXO1 and FOXO3 by blocking the PI3K-AKT pathway, and in turn induced cell-cycle arrest and apoptosis." (PMID 28938528, 2017). "Noteworthy, activation of FOXO proteins not only induces cell cycle arrest or apoptosis, but also a differentiation program.In chronic myeloid leukemia (CML), FOXO3 can induce CML leukemic cells differentiation, by inhibiting the expression of Id1 (Inhibitor of DNA binding 1)." (PMID 32309538, 2013).
Hyperglycemia (22 papers, 2013 to 2025). An increased concentration of glucose in the blood. "We found an interaction between FOXO3 variants and moderate physical activity on fasting hyperglycemia in long-lived individuals." (PMID 25993007, 2015). "In long-lived individuals, both single allele and haplotype analysis suggested a genetic association between FOXO3 block 1 and fasting hyperglycemia." (PMID 25993007, 2015). "The tagging single nucleotide polymorphism (tSNP) approach was used to compare the contribution of FOXO3 to risk of fasting hyperglycemia between LLI and middle-aged (MI_S and MI_N) subjects." (PMID 25993007, 2015). "The protective contribution of FOXO3 and PA to fasting hyperglycemia only existed in our long-lived individuals, suggesting that FOXO3 might be a shared genetic predisposition between hyperglycemia and lifespan." (PMID 25993007, 2015). "For hyperglycemia, the effect of modest variants in FOXO3 might be concealed by other major variants (e. g., PEPCK, PPARG and TCF7L2) in most studies based on middle-aged subjects." (PMID 25993007, 2015). "FOXO3 might act as a shared genetic predisposition to hyperglycemia and lifespan." (PMID 25993007, 2015). "It has been shown that Sirt1 exerts anti-inflammatory effects and reduces the hyperglycaemia-induced fibrosis of glomerular mesangial cells by promoting the transcriptional activity of the FOXO3 protein." (PMID 36232910, 2022). "In contrast, the silencing of SIRT1 resulted in the overexpression of the acetylated form of FOXO3, which potentiated hyperglycaemia-induced oxidative stress induced in renal tubules." (PMID 36232910, 2022). "In the present study, for the first time, we report the different genetic impact of FOXO3 on fasting hyperglycemia as an intermediated trait of healthy aging in long-lived individuals compared with middle-aged subjects (MI_S, MI_N)." (PMID 25993007, 2015). "Here, we performed a comprehensive analysis of FOXO3 and fasting hyperglycemia in three cohorts (n = 2037)." (PMID 25993007, 2015). "The PI3K/AKT pathway mediated hyperglycemia-induced apoptosis of NRVMs through the translocation of FOXO3a to nuclei and the resultant enhanced transcriptional activity of FOXO3." (PMID 24910802, 2014). "Our results show that DI-10 reversed the effects of hyperglycemia in skeletal muscle by activating protein synthesis through the Akt/mTOR pathway and preventing protein degradation by downregulating Murf-1 and MAFbx through FoxO3." (PMID 35454154, 2022). "However, no supportive evidence of FOXO3 variants has been reported to confer the risk for fasting hyperglycemia or type 2 diabetes (T2D) in middle-aged subjects of Indian origin." (PMID 25993007, 2015). "In addition, EGCG treatment of rat embryos blocks Forkhead Box O3 (FOXO3A) activation and reverses AKT inhibition, preventing hyperglycemia-induced embryopathy." (PMID 34371900, 2021).